DNMT3A (DNA methyltransferase 3 alpha)
Diseases named in the same sentence as DNMT3A in open-access papers (continued):
Sharing a sentence is not in itself a finding about the gene and the disease.
breast cancer (continued). "However, we found that knockdown of DNMT1, but not DNMT3a and DNMT3b, resulted in restoration of FOXO3a expression, indicating that the downregulation of FOXO3a is associated with DNMT1-mediated hypermethylation of its promoter in breast cancer." (PMID 31296961, 2020). "In addition, such future studies may include MTA1 knockdown with or without DNMT3a in breast cancer cells." (PMID 28393842, 2017). "At the TP53BP2 gene promoter in HeLa cells and the RASSF1A gene promoter in MDAMB-231 breast cancer cells, SETDB1 interacts with DNMT3A, but not with the maintenance methyltransferase DNMT1." (PMID 38904842, 2024). "At the TP53BP2 gene promoter in HeLa cells and the RASSF1A gene promoter in MDAMB-231 breast cancer cells, SETDB1 interacts preferentially with the de novo DNA methyltransferase DNMT3A, but not with the maintenance methyltransferase DNMT1." (PMID 38904842, 2024). "Interestingly, one study reported that DNMT3B expression was elevated in breast tumor subjects, but DNMT3A expression was not changed in breast cancer specimens in comparison to normal tissues, suggesting that deep exploration is necessary to determine the role of DNMT3A in breast cancer." (PMID 35620052, 2022). "Prior to VPA/hydralazine treatment, DNMT3a, DNMT1 or HDAC1 expression was not different in the mammary tumors of HF offspring, compared with controls." (PMID 31889127, 2019). "In summary, our data demonstrate that DNMT3a plays an important role in hypermethylation at CpG and non-CpG sites in MCF-7 cells and luminal subtype breast cancer tissue." (PMID 30940798, 2019). "In another word, although HIF-1alpha is primary regulated at the post-translational levels, there is transcriptional regulation of HIF-1alpha in breast cancer cells, such as the methylation at CpG and non-CpG dinucleotides in the HIF-1α promoter around the TSS which is mainly mediated by DNMT3a.." (PMID 30940798, 2019).
lung carcinoma (91 papers, 2008 to 2025). "Unlike our study, they found that mutations in ASXL1 exhibited a higher risk of lung cancer than DNMT3A and TET2." (PMID 40679991, 2025). "MiR-101 is another miRNA that targets DNMT3a in lung cancer; its overexpression is associated with reduced DNMT3a levels, global DNA methylation, and ultimately, the re-expression of CDH1." (PMID 37239435, 2023). "DNMT3A mutation is actually the main cause of blood system cancer, but recent studies have also proved its effect in lung cancer." (PMID 33633793, 2021). "Here, we observed an inverse correlation of IRX1 and DNMT3A or EZH2 expression in primary lung cancers suggesting a causal relation between aberrant expression of epigenetic modifiers and IRX1 silencing." (PMID 33256112, 2020). "Global DNA hypomethylation is associated with development of cancer, including lung cancer, which has been associated with Dnmt3a deficiency in mice." (PMID 28651580, 2017). "Having observed an inverse correlation between UHRF1/2 and DNMT3A proteins in lung cancer specimens, we next examined further the causal role of UHRF1/2 overexpression in downregulation of DNMT3A proteins in multiple lung cancer cell lines." (PMID 27462454, 2016). "In lung cancer, it was recently shown that the overexpression of DNMT3A protein was significantly associated with a lower overall survival." (PMID 24459426, 2013). "More recently, a study showed that a high level of DNMT3A protein expression was significantly associated with a lower overall survival in lung cancer." (PMID 19638978, 2009). "DNMT3A mutation happened in a variety of cancers such as colorectal cancer, lung cancer, chronic myelocytic leukemia, but is mainly with AML and usually occur with other types of mutations, such as FLT3, NPM1, C/EBP alpha, resulting in synergistic effects in AML." (PMID 36303144, 2022). "In KrasG12D-driven lung cancer models, deletion of Dnmt3a accelerates tumor growth, suggesting that DNMT3A can act as a context-dependent brake on proliferation, potentially reinforcing dormancy in early lesions." (PMID 41303477, 2025). "Given that DNMT3A/B can serve as an oncogene and a tumor suppressor gene in the lung cancer, the new inhibitors with selectivity toward DNMT1 and DNMT3A/B should be particularly highlighted in the new drug design of DNMT inhibitors (DNMTi)." (PMID 37628829, 2023). "Altered expression levels of DNMT1, DNMT3a, and DNMT3b proteins have been found in patients with lung cancers, especially in smokers, and are correlated with hypermethylation of tumor suppressor genes." (PMID 36959680, 2023). "Metformin dose-dependently downregulated expression of DNMT1 and DNMT3a at the post-transcriptional level and expression of DNMT3b at the transcriptional level in A549 lung cancer cells." (PMID 36959680, 2023). "Studies have demonstrated that DNMT3A affected the development of lung cancer cells (A549 cells) via the PTEN/PI3K/AKT signaling pathway." (PMID 36091786, 2022). "It is unclear if the specific role and expression levels of DNMT3A depend on different lung cancer histological types, as one study observed that DNMT3A was upregulated in SCLC but not NSCLC cell lines." (PMID 35205708, 2022). "DNMT3A also exerts as an oncogene in lung cancer by enhancing DNA methylation of the phosphatase and PTEN to reducing their expression." (PMID 35860691, 2022). "Previous study has demonstrated that SFRP1 is a Wnt antagonist and acts as a tumor suppressor by repressing lung cancer stem-cell like traits, and DNMT3A correlates the epigenetic silencing of SFRP1 gene." (PMID 35860691, 2022). "Data on the participation of DNMT3A in various types of carcinomas are now widely accepted and DNMT3A has been reported as a factor that is closely related to lung cancer, colorectal cancer, ovarian cancer, and liver cancer." (PMID 34148029, 2021). "METTL3 can promote the expression of multiple oncogenes such as BRD4, EGFR, TAZ, MAPKAPK2, and DNMT3A in human lung cancer cells." (PMID 34206803, 2021).
lung carcinoma (continued). "With regard to miRNAs contributing to DNA methylation dysregulation, it has been long described in lung cancer that the miR-29 family members target both DNMT3A and DNMT3B." (PMID 34298969, 2021). "Many demethylases have been involved in epi-miRNA reciprocal regulatory loops, such as DNMT3A with miR-29a/b in lung cancer and miR-200c in gastric cancer." (PMID 34298969, 2021). "These two completely opposite findings suggest that DNMT3A can act both as an oncogene and as a tumor suppressor gene in lung cancer." (PMID 32751889, 2020). "DNMT3B has been reported to be overexpressed in breast, oral, and colorectal tumor tissues, while other studies have suggested that DNMT3B and DNMT3A are tumor suppressor genes for lymphoma and lung cancer." (PMID 31024853, 2019). "Aberrant hypermethylation phenotype of tumor suppressor genes by DNMT3a activity has been reversed by expression of miR-101-3p in a model of lung cancer, where DNMT3 repression led to promoter hypomethylation and re-expression of tumor suppressor CDH1." (PMID 31864341, 2019). "MiR-101 affects lung cancer progression by targeting DNMT3A to regulate the PTEN/AKT signaling pathway." (PMID 29748607, 2018). "The expression of miR-29 family members are inversely correlated to DNMT-3a and -3b in lung cancer, directly targeting both DNMT3a and -3b." (PMID 26975503, 2016). "It has been suggested that miR-143 controls DNMT3A in colorectal cancer and that the miR-29 family regulates DNMT3A and 3B in lung cancer." (PMID 24710039, 2010). "In the case of lung cancer, the function of DNMT3A may be modified by SUMOylation a process of attaching and detaching small proteins called Small Ubiquitin-like Modifier (SUMO) to and from target proteins." (PMID 38982523, 2024). "This was significant to us, as loss-of-function mutations in DNMT3A are leading drivers of clonal hematopoiesis of indeterminate potential (CHIP), a highly inflammatory condition common in the elderly, and are strongly associated with lung cancer risk." (PMID 39236155, 2024). "Moreover, allelic loss of DNMT3A gene or loss of DNMT3A expression is frequently found in multiple human somatic tumor types; and depletion of Dnmt3a gene potently promotes progression of lung cancer with KrasG12D mutant in a mouse model." (PMID 37072414, 2023). "Additionally, miRNA-29b, down-regulates indirectly and directly DNMT1 and DNMT3A/3B expression respectively in AML patients and along with miRNA-29a cooperatively target DNMT3A/3B expression in lung cancer, while they are both down-regulated in AML." (PMID 36555712, 2022). "However, DNMT3A counteracted the inhibitory effect of miR-101 on the invasive migration of lung cancer cells and also disrupted the miR-101-activated caspase-3 (an apoptotic enzyme), which led to the inhibition of NSCLC proliferation." (PMID 36091786, 2022). "In addition to discoveries of roles in lung cancer, DNMT3A has recently attracted considerable attention due to its high expression in the tissues of CRC." (PMID 36091786, 2022). "The miRNAs (miR)-29 family (29a, 29b, and 29c), which have an intriguing complementarity with the 3’-UTRs of DNMT-3a and -3B, have been shown to be downregulated in lung cancer, which led to elevated expression levels of DNMT-3a and -3B associated with a poor prognosis." (PMID 35327559, 2022). "Above researches indicate that DNMT3A exerts an important role in lung cancer initiation and progression by enhancing DNA methylation on genes; therefore, DNMT3A and its target genes might act the potential therapeutic molecules." (PMID 35860691, 2022). "The miRNA-29 family, on the other hand, may restore aberrant methylation in lung cancer by targeting the 3'-untranslated region of DNMT3A and DNMT3B, which are typically overexpressed in lung cancer and are associated with a poor prognosis." (PMID 34820248, 2021).
lung carcinoma (continued). "MiR-29 family reverts abnormal methylation in lung cancer by targeting DNA methyltransferases 3A and 3B (DNMT3A and DNMT3B), induces re-expression of methylation-silenced tumor suppressor genes, such as FHIT and WWOX, and inhibits tumorigenicity in vitro and in vivo." (PMID 34299277, 2021). "miR-708-5p by targeting DNMT3A via repressing Wnt/β-catenin signaling could inhibit lung cancer stem cell-like phenotypes." (PMID 34368145, 2021). "Notably, the paradoxical role of DNMT3a that can act both as an oncogene and as a tumor suppressor gene in lung cancer has been proposed in a recent review." (PMID 33383878, 2020). "Similarly, it was reported that increased expression of DNMT3a led to the proliferation and metastasis of lung cancer cells." (PMID 33383878, 2020). "In this study, we found that ALDH2 expression could be induced by inhibiting DNMT3A expression, which indicated that ALDH2 can be regulated by DNMT3A, greatly reducing the probability of BM in lung cancer patients." (PMID 32850324, 2020). "In addition, Wei showed that miR‐30a suppressed the progression of lung cancer via regulating the p38 MAPK pathway by targeting DNMT3A in lung cancer." (PMID 32575164, 2020). "Similarly, increased expression of DNMT3A in lung cancer leads to the proliferation and metastasis of tumor cells." (PMID 32751889, 2020). "A previous study revealed that the reversion of the miR-29 family on abnormal methylation in lung cancer is mediated though regulation of DNMT3A and DNMT3B, two critical de novo DNA methyltransferases that are frequently upregulated in patients with idiopathic pulmonary fibrosis." (PMID 30906331, 2019). "Recently, DNMT3a has been shown to also serve as an independent prognostic marker in lung cancer where weak DNMT3a expression may result in a poor outcome." (PMID 28393842, 2017). "The role of DNMT3A in cell invasion has been observed in lung cancer." (PMID 27724883, 2016). "Thus, despite increased DNMT3A transcripts in lung cancers, DNMT3A at the level of proteins is actually substantially reduced in lung tumors, most likely as a consequence of targeted degradation of DNMT3A by overexpressed UHRF1/2." (PMID 27462454, 2016). "In addition, an inverse correlation between UHRF1/2 overexpression and DNMT3A proteins is also observed in lung cancer cell lines." (PMID 27462454, 2016). "Significantly, although RNA-seq data indicate increased DNMT3A transcripts in lung cancers, substantially reduced levels of DNMT3A proteins were actually detected in the tumors, and the levels of DNMT3A proteins exhibited a strong inverse correlation with that of the increased UHRF1 and UHRF2." (PMID 27462454, 2016). "However, in contrast to overexpression of DNMT3A in transcripts, reduced DNMT3A proteins were observed in our study by western blot analysis of lung cancer specimens." (PMID 27462454, 2016). "A recent experimental study in a mouse lung-cancer model suggests that the de novo methyltransferase Dnmt3a may be an important player in this process as it is required to maintain the fully-methylated state in active regions." (PMID 24550741, 2014). "The miR-29 family reverts aberrant methylation in lung cancer by targeting DNMT3a and DNMT3b." (PMID 24987964, 2014). "Consistent with Dnmt3a acting as a tumor suppressor gene, we have shown that deletion of Dnmt3a promotes tumor progression in a mouse model for lung cancer, thus providing a defined experimental system to investigate Dnmt3a-dependent methylome changes in cancer." (PMID 23284304, 2012). "Deletion of Dnmt3a in a K-ras–dependent mouse lung cancer model has been shown to promote tumor progression, which suggested that the enzyme might suppress tumor development by stabilizing DNA methylation patterns." (PMID 23284304, 2012).
lung carcinoma (continued). "For instance, lncRNA HOTAIR has been shown to associate with DNMT1, DNMT3A, and DNMT3B, which are concentrated in the promoter regions of genes associated with tumor metastasis, resulting in hypermethylation of these genes and promoting the metastatic potential of lung cancer cells." (PMID 41394878, 2025). "Interestingly, although DNMT3A has been reported to be overexpressed in lung cancers, there is evidence suggesting that DNMT3A might act as tumor suppressor." (PMID 35205708, 2022). "Moreover, miR-29 s expression is negatively correlated with DNMT3A and -3B in lung cancer." (PMID 34838029, 2021). "In this work, we deprioritized testing with DNMT3A because it has been reported that this enzyme can act as both an oncogene and as a tumor suppressor gene, at least in lung cancer (it remains to be tested as to whether this paradox of DNMT3A applies to other cancers)." (PMID 33375520, 2020). "Similarly, DNMT3a deletion in lung cancer promotes cancer progression." (PMID 28393842, 2017). "However, it leaves a question that whether DNMT3A acts the same in human lung cancer as in mouse lung cancer model." (PMID 28423585, 2017). "To analyze the gene expression of different DNMTs, we noticed an increasing trend in DNMT‐1, DNMT‐3A, and DNMT‐3B gene expression in hypoxic lung cancer cells compared to normoxia." (PMID 35658112, 2024). "DNMT-3A and B serve as targets for miRNA; miRNA-29 family members were the first discovered as epi-miRNAs due to their direct influences on DNMT-3A and B in lung cancer." (PMID 35740242, 2022). "The expression of DNMT3A and DNMT3B was high in lung cancer, and the expression of the miR-29 family was negatively correlated with them." (PMID 35478963, 2022). "Many studies have shown that AKT phosphorylation is regulated by DNMT3A via modulating the PTEN gene in various carcinomas, including pancreatic cancer and lung cancer." (PMID 34148029, 2021). "In our study, we found that TTTY15 was downregulated in lung cancer and was mainly located in the nucleus, upregulating TBX4 expression by targeting DNMT3A." (PMID 31311130, 2019). "The fungus dramatically increased GA up to 44.8 fold in the post-fermentation oolong tea extract (PFOTE), resulting in enhanced demethylation effects and a significant reduction in the nuclear abundances of DNMT1, DNMT3A, and DNMT3B in lung cancer cell lines." (PMID 29416619, 2018). "In lung cancer samples, we also observed a significant overexpression of HDAC1, HDAC2, HDAC6 and also DNMT1 and DNMT3A." (PMID 28634396, 2017). "Early stage lung cancers showed higher expression of TET1 and Dnmt3a than other advanced stages (p=0.011 and p=0.014 respectively)." (PMID 28680536, 2017). "For example, Sengupta and his colleagues have shown that miR-29c is down-regulated in nasopharyngeal carcinomas, while Fabbri and his colleagues discovered that the miR-29 family, including miR-29c, targets DNMT3A and DNMT3B in lung cancer tissues and cells." (PMID 23936390, 2013). "A recent study has revealed that miR-29 family (miR-29a, miR-29b, and miR-29c) target the de novo DNA methyltransferases DNMT3A and DNMT3B and expression levels of miR-29 family were suppressed in lung cancer." (PMID 23056009, 2012). "The reduced expression of the miR-29 family induced overexpression of DNMT3A and DNMT3B, resulting in aberrant DNA methylation in lung cancer." (PMID 23056009, 2012). "In addition, both DNMT3A and DNMT3B extend the epigenetic remodeling of lung cancer cells beyond the classical hypermethylation of promoter CpG islands." (PMID 41303477, 2025). "Our data identified the steady-state decline in DNMT3A as a contributing factor to the enhanced production of IL-1α by monocytic cells, providing novel mechanistic evidence for the relationship between CHIP, inflammaging, and lung cancer." (PMID 39236155, 2024).